RN7SL96P (RNA, 7SL, cytoplasmic 96, pseudogene)
Gene: Miscellaneous RNA gene on chromosome 2 (38,936,876 to 38,937,158, reverse strand). Ensembl gene ENSG00000265905.
Homologues: Orthologues: macaque Metazoa_SRP (86% identical). Paralogues in human: RN7SL774P (87% identical), RN7SL811P (87% identical), Metazoa_SRP (85% identical), RN7SL134P (85% identical), RN7SL474P (85% identical), RN7SL784P (85% identical), RN7SL391P (84% identical), Metazoa_SRP (83% identical), RN7SL488P (83% identical), RN7SL510P (83% identical), RN7SL163P (82% identical), RN7SL596P (82% identical), and 708 more.